TGFB1 (transforming growth factor beta 1)
Diseases named in the same sentence as TGFB1 in open-access papers (continued):
Sharing a sentence is not in itself a finding about the gene and the disease.
tumor (continued). "This process results in the production of cytokines like transforming growth factor beta-1 (TGF-β1), which recruit various inhibitory immune cells, including myeloid-derived suppressor cells, tumour-associated macrophages, regulatory T cells, and tumour-associated neutrophils." (PMID 39519230, 2024). "Additionally, TGFβ1-induced upregulation of PD-L1 in tumor cells has emerged as a novel mechanism of immunosuppression in NSCLC." (PMID 39737184, 2024). "In this study, we found that normal plasma 25(OH)D3 levels were associated with increased levels of TGFβ1 and β-catenin in tumor tissues (protein level assessed in the tumor tissues without sorting of tumor cells) compared to cases of vitamin D3 deficiency." (PMID 38360633, 2024). "In BC, miR-21’s tumor-promoting effects could be exerted by the regulation of transforming growth factor-beta (TGFβ) signaling, given that both TGFβ1 and its receptor TGFβR2 are putative targets of this miRNA." (PMID 38542114, 2024). "The observed effects of Rapamycin on tumor suppression are likely to involve the autophagy process, evidenced by the inhibition of autophagy modulators (TGFβ1, RGS19 and AKT1), autophagosome biogenesis components (AMBRA1, ATG9B and TMEM74) and autophagy byproducts (APP)." (PMID 38276004, 2024). "Moreover, the restoration of Tgfb1 expression in MC38 tumor cells had a comparable impact to exogenous TGF-β1 in mitigating the tumor suppression and CD44+CD8+ T cell activation induced by Atp6v0a1 depletion." (PMID 38971819, 2024). "Importantly, by surveying public databases, we observed significant positive correlations between PDCD1 and TGFB1 gene expression in most human tumor types." (PMID 38441961, 2024). "Moreover, treatment with CM from FHC cells incubated with mtDNA-rich EVs greatly promoted tumor cell proliferation, migration, and invasion, while the TGFβ1 inhibitors disitertide and LY364947 dramatically diminished this effect." (PMID 38688896, 2024). "Collectively, the data demonstrated that sGC deletion decreased TGFβ1 expression in the vascular niche, consequently reprogrammed adjacent CAFs into CD105neg apCAFs, potentially contributing to the observed phenotype of reduced tumor growth." (PMID 38528180, 2024). "Our result was consistent with the previous evidence that TGFβ1 shows higher and more widespread upregulation in the tumor microenvironment than the other two isoforms and is more robustly associated with failure of immune checkpoint inhibitor in patients with cancer." (PMID 38324026, 2024). "In our study, we considered TGFβ1 and interstitial fluidic flow as key factors that could alter cancer cell behavior in the tumor microenvironment, potentially affecting treatment outcomes." (PMID 38558874, 2024). "In addition, other factors, such as IL-10 and Transforming Growth Factor Beta-1 (TGF-β), secreted by M2 macrophages, inhibit Th1 lymphocyte responses and immune cell activation, creating an environment that supports tumor growth and immune evasion." (PMID 39769286, 2024). "Mechanistically, the intercellular mtDNA transfer activates the mitochondrial respiratory chain to induce the ROS-driven RelA nuclear translocation in CECs, thereby transcriptionally regulating TGFβ1 expression and promoting tumor progression via the TGFβ/Smad pathway." (PMID 38688896, 2024). "Moreover, the EV-mtDNA increases TGFβ1 expression in CECs, which in turn promotes tumor progression." (PMID 38688896, 2024). "Notably, the combined treatment of MEKi and TGFB1 mRNA further decreased tumor growth significantly compared to MEKi-only treated tumors." (PMID 39709491, 2024). "Hence, in agreement with our findings on fibroblasts differentiated into myofibroblasts via TGFβ1 treatment, both the proliferation and migration capacity of tumor cells were significantly inhibited by administration of the 3-Fax compound." (PMID 38920695, 2024).
tumor (continued). "Additionally, it regulates the transforming growth factor-beta 1 and basic fibroblast growth factor to inhibit tumor angiogenesis." (PMID 38728498, 2024). "Typically, macrophages infiltrated in tumors, named tumor-associated macrophages (TAM), shows M2-polarization characteristics and promote tumor malignant progression by secreting a variety of cytokines (e.g., TGFB1 and HMGB1) and chemokines (e.g., CCL17 and CXCL7)." (PMID 38576043, 2024). "Therefore, integrin αvβ6 interacts with pro-invasive membrane proteins at the tumor edge, e.g. the TGFβ type II receptor and the urokinase receptor, thereby promoting the proteolytic actions of TGFβ1 at the invasive tumor front." (PMID 38890650, 2024). "Our results might suggest an influence of the immunomodulatory cytokines CCL5, CCL18, GDF15, and TGFB1 on tumor progression." (PMID 39272860, 2024). "Moreover, silencing TGFβ1 expression in a tumor microenvironment can promote the differentiation of neutrophils into antitumor phenotypes." (PMID 38258086, 2024). "LRRC15-expressed fibroblasts surround tumor islets, and its expression was induced by TGFB1 (SE = 6.0); hence, it could be a marker of myCAFs rather than iCAFs." (PMID 38892190, 2024). "The fluorescence intensities of MCU, FOXP3, and TGFb1 were notably lower in the non-tumor group." (PMID 38632642, 2024). "Moreover, DKK3, TGFB1 and ECM1 have acted as immune-associated genes in the PCa tumour microenvironment." (PMID 38855324, 2024). "SPP1+ macrophages also exemplified high expression of TGFB1, suggesting an increase in TGFβ signaling towards tumor cells and fibroblasts that directly contribute towards fibroblast recruitment, cell proliferation and EMT, although TGFβ1 was high across all groups." (PMID 39075108, 2024). "S-III tumours exhibit more aggressive characteristics including the upregulation of proteins associated with a poor prognosis (such as TGFβ1, KRT19 and MMP9) and the activation of tumour-promotion pathways (such as TGFβ, HIF1, integrin and Rho GTPases pathways)." (PMID 39261716, 2024). "EVs from NSCLC also can expedite angiogenesis and tumor growth through a TGFβ1-dependent pathway." (PMID 39085238, 2024). "TGFβ1 might have antitumoral effects, but some studies suggest that both β-catenin and TGFβ1 can play tumor-supporting roles in cancer." (PMID 38360633, 2024). "OSCC mice without LD has similar TGFβ1 expression level but much higher than those undertaking surgical LD (two-way ANOVA, LD: P < 0.001, immunotherapy: P = 0.644), which was consistent with the cellular assay that neural involvement enhanced TGFβ signaling in tumor." (PMID 38324026, 2024). "Our data suggest that TGFB1 mRNA is not only present in the tumor but is indeed secreted by the tumor cells and could play a role in the development of VSs from vestibular nerves, which has not yet been investigated in VSs." (PMID 39272860, 2024). "We selected two additional tumor models, T11‐UV and T11‐Apobec, that displayed a high expression of Tgfb1 (both tumor models) and Tgfb2 (T11‐UV), high expression of Vimentin (Vim) and fibrotic marker (Pik3ca), and low expression of Cd36 and apoptosis regulator Bcl2." (PMID 39553439, 2024). "Classically, TGFβ1 is proposed to exert tumor suppressive roles in early-stage carcinogenesis." (PMID 39571651, 2024). "Chronic inflammation established by immune infiltration has been associated with tumor progression, particularly with enhanced metastasis and the EMT process through secreted factors such as transforming growth factor beta 1 (TGF-β1) and tumor necrosis alpha (TNF-α) derived from myeloid cells." (PMID 38086828, 2023). "However, real-time RT-PCR analysis showed significantly higher expression of Tgfβ1 in the tumor of S100a4-Cre; Ext1f/f mice." (PMID 36809261, 2023). "TGFB1 signaling also supports immunosuppression, promoting tumor development." (PMID 37653101, 2023).
tumor (continued). "Besides, higher expression of the TGFB1 gene was observed in tumor tissues from patients who resist to PD-1/PD-L1 antibodies." (PMID 37573354, 2023). "Furthermore, compared to the normal tissue, the HMOX1 and TGFB1 expression level in tumor tissue are mostly different in 33 tumor types." (PMID 37653101, 2023). "However, in our study, the anti-PD-L1 antibody treatment showed an increase in TGFβ1 expression in high PD-L1 expression tumor cells." (PMID 38152616, 2023). "Furthermore, we demonstrated that FAM3C up-regulation in neutrophils is through tumor-derived TGFβ1." (PMID 37056931, 2023). "We also confirmed the increased expression of Tgfb1 and Tnf in tumor tissues." (PMID 37845228, 2023). "With respect to the gene expression profile, CCL21 increased the expression of tumor-supportive genes such as Vegfa, Mrc1, Arg1, and Cd274 (PD-L1) in microglia, as well as in BMDMs that also showed increased expression of Il-10 and Tgfβ1." (PMID 37314567, 2023). "Consistent, significant, and gradual elevation in the expression of TGFβ1 in primary tumours versus normal kidney tissues; and between metastatic and primary tumours, and in different stages of ccRCC compared to normal tissues indicate a role of TGFβ1 in the progression of ccRCC." (PMID 37174052, 2023). "Inhibition of PDGFRB signaling could result in the down-regulation of IL6 and TGFB1/2 in CAFs and suppressed expression of immune checkpoints in tumor cells, leading to immune cytotoxicity." (PMID 37658364, 2023). "Conversely, in late-stage cancers, tumor cells could rewire the TGFβ1 pathway to avoid apoptosis and suppress immune responses, which promotes tumor progression." (PMID 37925591, 2023). "Thus, we concluded that coculture with platelets promoted the malignancy of tumor cells by inducing TGFβ1 secretion and activating the TGFβ/Smad signalling pathway." (PMID 37705745, 2023). "This suggests that at least in the models tested, the level of TGFβ1-3 in the tumor may contribute to resistance to oncolytic VV therapy." (PMID 37552475, 2023). "Besides, the hypoxia environment induces the EMT by enhancing the expression of EMT-promoting genes, such as SNAI1, SNAI2, TWIST1, and TGFβ1, which ultimately stimulates the migration of tumor cells to distant tissues." (PMID 37784157, 2023). "Areas of SCF immunostaining were also found in the tumor-like cells (enlarged photograph of black frame), as well as in the fibroblast-like spindle cells (enlarged photograph of green frame), whereas TGFβ1 immunostaining was mainly found in the tumor-like cells (enlarged photograph of black frame)." (PMID 37175975, 2023). "ANGPTL8 may be induced by STAT3 signalling, FFAs or other proinflammatory cytokines, such as TNF-α and TGFβ1, in the tumour microenvironment, and it may affect the differentiation and development of tumours through the following pathways." (PMID 38107478, 2023). "In addition, except for TIMP1 (P > 0.05), the expression levels of INHBA (P < 0.05), LAMC2 (P < 0.05), PLAU (P < 0.05) and TGFβ1 (P < 0.05) were significantly different between tumour and normal samples." (PMID 37325056, 2023). "Interestingly, iTregs also produce both IL10 and TGFβ1, are found in solid tumour infiltrates and are indicative of a poor anti-tumour response during cancer progression." (PMID 36973425, 2023). "Among invaded tumor cells, the c4 subgroup had elevated expression of TGFB1." (PMID 38187400, 2023). "Since the contribution of TGFβ1 to EMT may be contextual, we mimicked the high levels of TGFβ1 secreted by the tumor microenvironment in vitro through treatment of single cell seeded organoid cultures with recombinant TGFβ1." (PMID 36828915, 2023). "Since we observed in our own patient cohorts that high levels of serum TGFβ1 in PDAC patients increased with the stage of the tumor, we further explored the relationship between TGFβ1, organoid morphology, and high-grade tumors by establishing MO allograft models." (PMID 36828915, 2023).
tumor (continued). "Its effect against TGFβ1, which boosts the tumor cell invasion was examined." (PMID 37197584, 2023). "To clarify these contradictory results, we studied if NDRG1 and/or p-NDRG1 (Thr346) could be involved in tumor aggressiveness mediated by TGFβ1." (PMID 36594086, 2023). "However, during the later stages of tumor development, TGFβ1 functions as a tumor promoter by inducing the epithelial-mesenchymal transition (EMT) in cancer cells, resulting in increased invasion and metastasis." (PMID 37033970, 2023). "EMT can be induced by different factors (TGFβ1, TNFα, etc.)secreted by different cells in a tumor." (PMID 37108080, 2023). "We showed that C3a plays a crucial role in the tumor microenvironment and may influence the tumor’s fate by modulating the expression of cytokines (including IL-10, TGFβ1), chemokines, Cox-2, and HO-1, and upregulating the oxidative stress response." (PMID 37296948, 2023). "Herein we proved a robust evidence in support of in vivo interaction between GATA2 and SMAD4 and thus sought to unravel the mechanistic roles of TGFβ1/SMAD4 in the GATA2-dependent context in PCa tumor progression to advanced stages and to understand how GATA2 and SMAD4 mediate inherited PCa risk." (PMID 37550764, 2023). "In OC, TAMs are predominantly M2 macrophages that produce and secrete anti-inflammatory/immunosuppressive cytokines such as IL-10 and transforming growth factor beta 1(TGFB1) and chemokines (CCL17, CCL18, and CCL22) associated with tumor invasion, angiogenesis, metastasis, and early recurrence." (PMID 37298230, 2023). "Furthermore, inhibiting TGFB1 release reduced tumor stromal fibrosis, opened blood vessels, and enhanced the efficacy of the standard chemotherapy regimen, thereby significantly improving the survival of the orthotopic tumor‐bearing mice." (PMID 37789644, 2023). "Tumor cells use TGFβ-1 to prevent tumor recognition and promote angiogenesis." (PMID 37509493, 2023). "In addition to the canonical pathway involving SMAD proteins that mediate the effect of TGFβ1 in promoting EMT, activation of MAPK family proteins has also been reported to be required for full induction of the EMT by TGFβ1 in tumor cells." (PMID 37476896, 2023). "Moreover, expression of this gene set and TGFβ1 pathway activity were correlated in various tumor transcriptomes and turned out to be predictive of poor prognosis in several tumor entities." (PMID 36672507, 2023). "Thus, TRPV1 blockade plays an important role in suppressing MDSCs through the aPD-L1 infiltration and TGFβ1 modulation in tumor." (PMID 37120615, 2023). "We observed a higher expression level of TGFB1 in the EIC than in the rest class, and this is consistent with Mariathasan’s study which found cytokine TGFβ (encoded by TGFB1) suppressed anti-tumour immunotherapy." (PMID 35799269, 2022). "Tumor-promoting genes, including TGFβ1, were more likely to be packaged into LLPS droplets." (PMID 36209170, 2022). "TGFβ1 is well known to facilitate tumor formation and development." (PMID 35033156, 2022). "Again, this might point to a particularly strong canonical WNT activity in the CRLM of poor-outcome patient I. It must be mentioned that TGFB1 can act both as a tumor suppressor and a tumor promoter, depending on the cellular context." (PMID 35565214, 2022). "TGFβ1 facilitates rapid tumour proliferation, while TGFβ2 promotes tumour cell dormancy." (PMID 36307871, 2022). "Finally, CDH17 ‘high-methylation’ tumours display significantly increased TGFB1 expression when compared to CDH17 ‘low-methylation’ CC tumours." (PMID 36612154, 2022). "This phenomenon implies that, in progressive TBSCC, TGFβ1, which is both released from destroyed bone and secreted from the tumor cells themselves, could induce EMT." (PMID 35562926, 2022). "In an environment containing TGFβ1, the number of tumor spheroids formed was increased." (PMID 36474273, 2022).
tumor (continued). "CD14CTX had increased expression of several tumor-associated macrophage (TAM)- and/or myeloid-derived suppressor cell (MDSC)-related cytokines, including IL6, TGFB1, and CXCL8." (PMID 36130508, 2022). "However, tumor cells hijack the tumor-suppressive responses to TGFB1 and convert this signal into an oncogenic factor." (PMID 35179962, 2022). "However, as the cancer progresses, immunosuppressive TGFβ1 that originates from the primary tumor microenvironment, and platelets, can induce N2 neutrophil polarization, which aids in CTC survival and epithelial–mesenchymal transition (EMT)." (PMID 35207611, 2022). "However, only the TGFβ1 data exhibited statistically significant overexpression, which was proportional to the respective values of mALN diameter of tumor deposits." (PMID 35658894, 2022). "Meanwhile, an opposite trend was observed for TGFB1 expression in these tumor tissues." (PMID 35853880, 2022). "We believe this study expands our understanding of TGFB1/EZH2-mediated tumor metastasis." (PMID 35085106, 2022). "TGFβ1 has been extensively investigated as an immunosuppressive factor in tumour settings." (PMID 36011012, 2022). "Latent TGFβ1 is expressed in diverse tumor cells and can be activated by binding to ITGB8." (PMID 35676251, 2022). "Besides, several tumor-related genes, like VEGFA, TBX2, and TGFB1, were also enriched in the high-risk group." (PMID 36203430, 2022). "Further, CD4+ T cells cultured in the presence of B7x+ tumor cells expressed Foxp3 at greater rates than those cultured with B7x- tumor cells, consistent with our in vivo findings, and this effect was diminished by the addition of anti-TGFβ1 blocking antibody into the culture." (PMID 35523809, 2022). "Once EZH2 is amplified in cancer cells, TGFB1-mediated gene expression might be more vulnerable to activation and further facilitate tumor progression." (PMID 35085106, 2022). "At the same time, they expressed TGFB1 to promote fibroblast activities, and as a result, both the two pathways may support tumor growth and depress normal immunocytes, like T cells." (PMID 35783506, 2022). "M2 macrophages can be further classified into different subtypes, namely M2a (mediated by IL4 and IL13), M2b (mediated by immune complexes (IC) with LPS or IL1R ligand), M2c (mediated by TGFB1, IL10, and glucocorticoids), and M2d (activated by tumor-associated factors, the major part of TAMs)." (PMID 36211379, 2022). "When TGFβ1-deficient platelets were incubated with tumor cells, no significant increase in metastasis foci was observed, suggesting that platelet-derived TGFβ1 is essential." (PMID 35659308, 2022). "Moreover, TGFB1 was involved in the whole process of tumor migration, bone colonization, dormancy, and bone resorption and remodeling." (PMID 35872837, 2022). "Vigil (gemogenovatucel-T) is a novel plasmid engineered autologous tumor cell immunotherapy designed to knock down the tumor suppressor cytokines, TGFβ1 and TGFβ2, augment local immune function via increased GMCSF expression and enhance presentation of clonal neoantigen epitopes." (PMID 36051466, 2022). "(A) MC38 tumor cells were implanted subcutaneously in WT and Piezo1-/- mice (n=10), IL-12 100 ng or anti-TGFβ1 mAb 200 ng per mouse in 50 μl volume or vehicle (PBS) was locally injected into tumor once a week and tumor size was measured every 5 days for 40 days." (PMID 35993548, 2022). "Additionally, macrophages and cancer associated fibroblasts present in the tumour microenvironment can secrete classical EMT-inducing cytokines/chemokines including HGF, SDF1α, EGF, PDGF as well as TGFβ1." (PMID 35203300, 2022). "Smad-2 is phosphorylated via TGFβ1/TGFβ1 receptor signaling, which acts in tumor progression." (PMID 35650563, 2022).